CLUHP3 (clustered mitochondria homolog pseudogene 3)
Synonyms: MGC3020; formerly C16orf67; KIAA0664P3; KIAA0664L3
Gene: Transcribed unprocessed pseudogene on chromosome 16 (31,703,168 to 31,708,581, forward strand). Ensembl gene ENSG00000131797.
Diseases named in the same sentence as CLUHP3 in open-access papers:
CLUHP3 is named in the same sentence as 1 disease in open-access papers, as found by Europe PMC text mining. Sharing a sentence is not in itself a finding about the gene and the disease. The quoted sentences say what the papers report.
tumor (1 paper, 2022). "The composite plot indicated that SDHAP1, SDHAP3, DDX12P, CLUHP3, and RRN3P3 demonstrated high expressions in the low-risk subtype, which were categorized as tumor-suppressor pseudogenes in our study." (PMID 36438489, 2022). "Compared to HPV negative, patients with HPV positive had significantly higher expressions of oncogene pseudogenes (SDHAP1, SDHAP3, DDX12P, CLUHP3, and RRN3P3), but there was no prominent difference in the expressions of tumor-suppressor pseudogenes (PDIA3P1, LDHAP4, LDHAP7, EEF1A1P6, and EEF1A1P11)." (PMID 36438489, 2022).